SOX9 (SRY-box transcription factor 9)
Diseases named in the same sentence as SOX9 in open-access papers (continued):
Sharing a sentence is not in itself a finding about the gene and the disease.
ovarian carcinoma (continued). "Recent studies have also demonstrated that cytoplasmic SOX9-mediated cell death inhibition contributes to the survival of cancer stem cells in high-grade ovarian cancer." (PMID 36003340, 2022). "Since cancer stemness was associated with ovarian cancer progression and prognosis, next, we explored the effect of SOX9 gene silencing on the cancer stemness of ovarian cancer cells." (PMID 35159173, 2022). "In order to explore the unusual cytoplasmic localization of SOX9 protein in lymph node metastatic HGOC, we screened human ovarian cancer cells for SOX9 expression level and its subcellular localization." (PMID 35159173, 2022). "For instance, LINC00115 can function as a ceRNA by acting as miR‐30a sponge to indirectly regulate SOX9 expression and promote stemness of ovarian cancer." (PMID 34697900, 2021). "In the current study, we found that miR-30a-mediated DEGs are involved in the regulation of key biological processes of ovarian cancer, such as SOX9, transcription factor 21 (TCF21), Wnt-5a,etc." (PMID 33004058, 2020). "Clinical relevance of SOX9 in ovarian cancer relies on its coexpression with HIF-2α under hypoxia conditions, promoting TUBB3 expression." (PMID 31057614, 2019). "In another study, ST6Gal-1 has been reported to regulate stemness and gemcitabine resistance in pancreatic and ovarian cancer by modulating SOX9 and SLUG expression." (PMID 30466404, 2018). "Some pre-clinical work suggested that SOX9 expression contributes to aggressiveness and invasiveness in ovarian cancer, but clinical data are currently sparse." (PMID 29121666, 2017). "This is also relevant to the clinical situation that Twist and Sox9 are often elevated in malignant ovarian tumors and confer a poor outcome to the late stage ovarian cancer patient survival." (PMID 27191261, 2016). "It is also relevant to the clinical situation that Twist and Sox9 are often elevated in malignant ovarian tumors and Twist expression confers a poor outcome to the late stage ovarian cancer patient survival." (PMID 27191261, 2016). "Thus, our data indicated that USP28 cooperates with SOX9 to promote resistance to olaparib in ovarian cancer." (PMID 40240356, 2025). "However, the regulation of SOX9 stability via ubiquitin modification in ovarian cancer remains poorly understood." (PMID 40240356, 2025). "Furthermore, the USP28 specific inhibitor AZ1 reduced SOX9 protein stability and increased the sensitivity of ovarian cancer cells to olaparib." (PMID 40240356, 2025). "Thus, our data indicated that USP28/SOX9 promotes olaparib resistance in ovarian cancer by regulating the DDR activity." (PMID 40240356, 2025). "Further mechanistic studies indicate that targeted inhibition of USP28 using a specific inhibitor leads to ubiquitination-mediated degradation of SOX9, consequently inhibiting DNA damage repair capabilities, and ultimately enhancing the sensitivity of ovarian cancer to PARPi." (PMID 40240356, 2025). "Moreover, the overexpression of SOX9 has been shown to stimulate metastasis and proliferation of ovarian cancer cells." (PMID 40240356, 2025). "Furthermore, inhibition of USP28 was shown to overcome PARPi resistance in ovarian cancer by regulating SOX9 protein stability both in vitro and in vivo." (PMID 40240356, 2025). "We then turned to explore the mechanism by which SOX9 regulates PARPi resistance in ovarian cancer." (PMID 40240356, 2025). "Accumulating experimental and clinical data reveal an important role of SOX9 in tumor development due to its overexpression and strong correlation with tumor progression and metastasis in a wide range of human cancers including ovarian cancer." (PMID 35159173, 2022). "The marked induction of cell death to the standard CDDP treatment in human ovarian cancer cells and complete inhibition of sphere formation and cancer cell invasion suggest the potential therapeutic effect of SOX9 silencing in human ovarian cancer." (PMID 35159173, 2022).
ovarian carcinoma (continued). "Moreover, Hexokinase 2 regulates the metastasis, invasion, and cell stemness of ovarian cancer cells through the FAK/ERK1/2/MMP9/NANOG/SOX9 signal transduction pathways." (PMID 34596006, 2021). "Apart from that, Sox9 expression is upregulated by hypoxia in ovarian cancer." (PMID 27105493, 2016). "In addition to the effects on cell migration and invasion, we believe our identification of the downstream pathways of HK2—Namely the HK2 to FAK to MEK-1/ERK1/2 pathway that controls NANOG and SOX9 expression and ovarian cancer CSC properties—Will be of significant importance to future studies." (PMID 31212816, 2019). "In conclusion, these findings suggested that USP28/SOX9 positively regulates the expression of DDR genes (SMARCA4, UIMC1, and SLX4) by binding to their promoters in ovarian cancer cells." (PMID 40240356, 2025). "However, the function of SOX9 in the PARPi resistance of ovarian cancer remains unclear." (PMID 40240356, 2025). "ChIP-Seq analysis revealed that SOX9 binds to the promoters of key DNA damage repair (DDR) genes (SMARCA4, UIMC1, and SLX4), thereby regulating DDR processes in ovarian cancer." (PMID 40240356, 2025). "In ovarian cancer, the gene set enrichment analysis (GSEA) of FLNB and SOX9 genes revealed distinct and overlapping pathway involvements." (PMID 38529261, 2024). "We selected 2774 cells due to its high SOX9 mRNA and cytoplasmic SOX9 protein expression found in HGOC samples and human ovarian cancer cell lines." (PMID 35159173, 2022). "Consistent with the interaction results in a yeast system, a co-immunoprecipitation assay with anti-SOX9 and anti-RIPK1 showed an interaction between them in ovarian cancer cells." (PMID 35159173, 2022). "Prevention of cancer cell death by protein interaction between stemness-regulating SOX9 and RIPK1 contributes an evasion of an apoptotic cell death in devastating ovarian cancers." (PMID 35159173, 2022). "We observed colocalization of both SOX9 and RIPK1 proteins in the cytoplasm, supporting their interaction in human ovarian cancer cells." (PMID 35159173, 2022). "Genes significantly downregulated by ALDH1A1 inhibition included stem cell markers (CD44, FZD7, and SOX9) and genes involved in chemoresistance (ABCB1 and NFκB) in ovarian cancer." (PMID 35884498, 2022). "Next, to confirm SOX9-RIPK1 interaction in human ovarian cancer cells, MDAH 2774 cells with high SOX9 and RIPK1 protein levels were subjected to immunoprecipitation followed by immunoblotting." (PMID 35159173, 2022). "In conclusion, HK2, which is regulated by the tumor microenvironment, controls lactate production and contributes to ovarian cancer metastasis and stemness regulation via FAK/ERK1/2 signaling pathway-mediated MMP9/NANOG/SOX9 expression." (PMID 31212816, 2019). "GEPIA further revealed a significant clinical correlation between NANOG, OCT4, KLF4, SOX9, and CD117 and HK2 expression (p < 0.05) in ovarian cancer clinical samples." (PMID 31212816, 2019). "However, we could further show that SOX9 positivity was associated with poor clinical outcome not only in HCCs but also in lung, breast, gastric and ovarian cancer." (PMID 29121666, 2017). "As inhibitors specifically targeting SOX9 are not yet available, we focused on elucidating the mechanisms driving its upregulation in ovarian cancer cells upon olaparib treatment." (PMID 40240356, 2025). "By analyzing the correlation between DYRK3 and EMT-related genes in TCGA-ovarian cancer dataset, we observed a positive correlation between DYRK3 with FLNB and SOX9, both of which had been well acknowledged as oncogenic molecules in tumorigenesis and cancer progression." (PMID 38529261, 2024). "Additionally, in pancreatic and ovarian cancer cells, ST6GAL-1 has been shown to induce the expression of CSC-specific TFs, such as Sox9 and Slug." (PMID 32927726, 2020). "For example, SOX9, MYB, and ESRP1 promote ovarian cancer cell proliferation." (PMID 32076467, 2020).
ovarian carcinoma (continued). "Clinical, in vitro and in vivo evidence strongly suggested that upregulation of HK2 in ovarian cancer was correlated with metastasis and poor survival and mediated migration, invasion and stemness via PTK2/MAPK1/3/MMP9/NANOG/SOX9 signaling cascades in vitro and in a nude mouse model." (PMID 33052246, 2020). "Besides NANOG and SOX9, we also revealed an up-regulation of OCT4, KLF4, and CD117 by HK2 in ovarian cancer, which further supports the concept that HK2 regulates CSCs." (PMID 31212816, 2019).
liver cancer (30 papers, 2013 to 2025). An epithelial or non-epithelial malignant neoplasm that arises from the liver. "To explore the involvement of DNMT1 in the Sox9-mediated reduction in AY/AN-cHCC-CCA, we delivered a plasmid expressing full-length Dnmt1 into Sox9 CKO mice to investigate its association with SOX9 during liver cancer development." (PMID 39273023, 2024). "Higher expression of SOX9 promotes stemness and tumorigenesis in liver cancer stem cells and is also associated with poor survival." (PMID 35563098, 2022). "In tumor samples from liver cancer patients, high SOX9 expression is associated with advanced tumor stage, higher tumor grade, poorer recurrence-free survival, and poorer overall survival." (PMID 34083580, 2021). "However, whether these SOX9+ cells play a role in liver carcinogenesis has not been fully understood, although high SOX9 expression has been linked to poor survival outcome in liver cancer patients." (PMID 34083580, 2021). "In terms of HCC, a recent study has proven that high SOX9 expression levels indicate tumor aggressiveness in liver cancer and enhance sorafenib resistance by modulating ATP binding cassette sub-family G member 2(ABCG2) expression." (PMID 40428248, 2025). "This suggests that focusing the model’s attention on the tumor and its surrounding areas helps improve its prediction of SOX9 expression in liver cancer patients." (PMID 40428248, 2025). "This further supports our claim of overlapping and/or context/stage-dependent roles for SOX9 in liver cancer including CCA." (PMID 39273023, 2024). "Recent studies have underscored the context-dependent roles of SOX9 in liver cancer formation in a preventive manner." (PMID 39273023, 2024). "The contrasting outcomes observed between developmental Sox9 elimination and tumor-specific acute Sox9 ablation highlight the nuanced functions of SOX9 in liver cancer biology." (PMID 39273023, 2024). "In the current study, we mainly used the SB-HDTVI-based Akt-YAP1 and Akt-NRAS HC-derived cHCC-CCA models to investigate the roles of Sox9 in the liver cancer setting, including cHCC-CCA." (PMID 39273023, 2024). "This indicates context-dependent roles for SOX9 in fate control and cell viability within the mammalian liver cancer." (PMID 39273023, 2024). "In the Pten-deleted Sox9+ cells, liver cancer was found with mixed-lineage tumors of both HCC and intrahepatic cholangiocarcinoma." (PMID 38332150, 2024). "In liver cancer, high SOX9 expression correlates with advanced tumor stage, higher tumor grade, poorer recurrence-free survival, and poorer overall survival." (PMID 34083580, 2021). "Our study, by specifically targeting Pten deletion to SOX9+ cells provides strong evidence that these cells are capable of serving as TICs in the liver and likely contribute to the heterogeneity observed in liver cancer." (PMID 34083580, 2021). "According to the reports of the literature, miR-520f-3p is functional in liver cancer and GC 44, 45, and targeting of SOX9 by miR-520f-3p regulated the sensitivity to targeted therapy and cancer stem cell phenotype 44." (PMID 33500736, 2021). "We report that liver injury, which occurs with chronic steatosis, induces the proliferation of the Pten deletion transformed SOX9+ liver TICs and promotes liver cancer development." (PMID 34083580, 2021). "Collectively, our findings suggest that JMJD2D promotes LCSC self-renewal by enhancing EpCAM and Sox9 expression via Wnt/β-catenin and Notch signaling pathways and is a potential therapeutic target for liver cancer." (PMID 33434575, 2021). "Our findings suggest that FXR represses Notch1 expression and directs ACD of Sox9+ cells to prevent the development of liver cancer." (PMID 33845903, 2021). "This study demonstrates the nature of SOX9+ cells as the cellular origin for liver cancer and implicates their roles in liver cancer heterogeneity." (PMID 34083580, 2021).
liver cancer (continued). "Restoration of EpCAM and Sox9 expression in JMJD2D-knockdown liver cancer cells rescued the self-renewal of LCSCs." (PMID 33434575, 2021). "Meanwhile, FXR also positively regulated Numb expression, contributing to a feedback circuit, which decreased Notch1 activity and directed Sox9+ cells asymmetric division to prevent the development of liver cancer." (PMID 33845903, 2021). "Our results suggest that TFEB-mediated upregulation of Sox9 expression plays a role in liver cancer development by inducing progenitor cell proliferation." (PMID 32424153, 2020). "Moreover, knockout of NF2, DYRK1A, and SOX9 in another TSPAN8-expressing human liver cancer cell line, SNU878, similarly resulted in a downregulation of TSPAN8." (PMID 40801599, 2025). "Furthermore, a high SOX9 expression correlates with tumor aggressiveness in liver cancer and enhances sorafenib resistance by modulating the expression of ATP-binding cassette sub-family G member 2 (ABCG2)." (PMID 40428248, 2025). "Additionally, FXR regulates asymmetric cell division of Sox9+ cells via the Notch1 pathway to prevent liver cancer development." (PMID 39940889, 2025). "Reminiscent of human liver cancers that express both lineages, we noted the upregulated expression of stemness markers such as Sox9, Sox4, Cd44, Prom1 and Cd24a in HepYF-M13 and HepYF-M14 cells compared to their expression in normal hepatocytes and H2.35 immortalized hepatocytes." (PMID 39051113, 2024). "This implies a distinct role for SOX9 in liver cancer lineage." (PMID 39273023, 2024). "CXCL5 has been identified as a crucial mediator downstream of the transcription protein sex-determining region Y-box 9 (Sox9) and since Sox9 is required for the self-renewal and tumor propagation of liver cancer stem cells (CSCs; 35); it has been characterized as a candidate CSC marker of HCC." (PMID 38252699, 2024). "However, in contrast to Sox9 LKO or YAP1 alone-mediated liver cancer studies, acute Sox9 disruption using the CRISPR/Cas9 system robustly repressed Akt-YAP1 cHCC-CCA formation, irrespective of tumor fate." (PMID 39273023, 2024). "Given the widespread expression of SOX9 in fully developed Akt-YAP1 or Akt-NRAS CCA regions as well as poorly differentiated HCC regions, we delivered SB-STOP(flf)−Cas9-sg-Sox9 along with the Akt-YAP1 or Akt-NRAS plasmid into OPN-CreERT2 mice to induce liver cancer." (PMID 39273023, 2024). "Moreover, induction of YAP1 by NOTCH can promote the expression of SOX9 and EpCAM stemness markers in liver cancer." (PMID 36045416, 2022). "Furthermore, we found that the expression of JMJD2D, EpCAM, and Sox9 was upregulated in human liver cancer specimens in GEO database, and the mRNA levels of JMJD2D were positively correlated with EpCAM and Sox9 in TCGA database." (PMID 33434575, 2021). "In addition, SNHG10 regulates the expression of SOX9 to promote cell invasion, proliferation, migration and epithelial–mesenchymal transition in liver cancer, suggesting its role as an oncogenic lncRNA." (PMID 32843060, 2020). "As patients with chronic liver disease are more likely to develop liver cancer, reduction of Sox9 expression as a means to promote LPC-to-hepatocyte differentiation in patients with chronic liver disease may also reduce liver tumorigenesis." (PMID 30992706, 2019). "Reduced SOX9 expression by siRNA decreased the growth of liver cancer cells (p<0.05)." (PMID 29121666, 2017). "In our gene silencing assay we could confirm these results demonstrating that siRNA against SOX9 reduced growth of liver cancer cells." (PMID 29121666, 2017). "In conclusion, our study supports the hypothesis that SOX9 is involved in liver cancer proliferation and HCC stem cell capabilities." (PMID 29121666, 2017). "Upregulation of liver cancer stem markers, Sox9, Epcam and Dmbt1 were observed in this study." (PMID 23630614, 2013).
liver cancer (continued). "Therefore, we speculate that, in this zebrafish liver cancer model, Sox9 may regulate hepatocyte dedifferentiation through the Wnt–mTOR signaling pathway." (PMID 35563098, 2022). "Despite this, the significant and robust reduction in HA-tag+ liver cancer specifically in Akt-YAP1 Sox9 iKO livers indicates the context- and oncogenic driver-dependent therapeutic potential of Sox9 elimination in advanced Akt-driven cHCC-CCA tumors." (PMID 39273023, 2024). "Collectively, these results indicated that SOX9 and SMAD2 acted downstream of YAP-signaling potentially increase transcriptional diversity in liver cancer patients." (PMID 35322024, 2022). "Other studies have shown that MKLN1-AS is regulated by SOX9 transcription and enhances the effect of SOX9 on the proliferation and epithelial-mesenchymal transition (EMT) of liver cancer cells." (PMID 36081999, 2022). "A study in liver cancer also demonstrated that YAP and SOX9 play a similar role in determining hepatocyte plasticity, transitioning from mature hepatocytes to progenitor cells, consistent with YAP and SOX9 being both enriched in the non‐NE subtype." (PMID 39372390, 2024). "A recent study led by Dr. Yang’s group demonstrated two dominant roles for SOX9 in YAP1 alone-driven liver cancer: indispensable roles in lineage determinants for HC-to-iCCA formation and responsibility for the severity of YAP1-HCC using AAV8-Cre;Sox9(f/f)-mediated Sox9 ablation." (PMID 39273023, 2024). "In this study, we explored the tumor initiating ability of SOX9+ cells given the high negative correlation between SOX9 expression and liver cancer survival." (PMID 34083580, 2021). "To address this question, we developed a liver cancer mouse model (PtenloxP/loxP; Sox9-CreERT+; R26RYFP) where tumor suppressor Pten (phosphatase and tensin homolog deleted on chromosome ten) is deleted in SOX9+ cells following tamoxifen injection." (PMID 34083580, 2021). "The ability of SOX9+ cells to contribute to liver cancer formation in vivo however had heretofore not been established." (PMID 34083580, 2021). "In addition, we overexpressed miR-126 or/and HOXB6 in liver cancer cell lines, respectively, and we found that overexpression of HOXB6 abrogated miR-126-induced increases in stem cell-related gene SOX9 expression." (PMID 32763157, 2020). "Interestingly, therapeutic Sox9 iKO significantly decreased Akt-YAP1 tumor burden at 6–8 weeks post-HDTVI, bringing the LW/BW ratios down to 4–5, which is comparable to mice without tumors, suggesting a strong therapeutic effect in Akt-YAP1-driven liver cancer." (PMID 39273023, 2024). "Out of the six Sox9-Pten mice on HFD, only one did not develop liver cancer." (PMID 34083580, 2021).